RCAN1 (regulator of calcineurin 1)
Diseases named in the same sentence as RCAN1 in open-access papers (continued):
Sharing a sentence is not in itself a finding about the gene and the disease.
autoimmune disease (1 paper, 2018). A disorder resulting from loss of function or tissue destruction of an organ or multiple organs, arising from humoral or cellular immune responses of the individual to their own tissue constituents. "This study broadens our understanding of regulation of TLR signaling in innate immunity and suggests that RCAN1 could be a potential therapeutic target in many inflammatory and autoimmune diseases with dysregulation of TLR signaling." (PMID 29799862, 2018).
B cell lymphoma (1 paper, 2012). "In this study, we knocked out FKBP5 and RCAN1 alleles independently in a human pre-B cell lymphoma cell line, Nalm-6, by gene targeting." (PMID 23185487, 2012).
bladder cancer (1 paper, 2022). "The levels of RCAN1 in urine samples of the bladder cancer group were lower than those in the control group." (PMID 35717152, 2022). "The diagnostic value of RCAN1 levels was higher than negative cytology—a common noninvasive diagnostic method for bladder cancer." (PMID 35717152, 2022). "Similarly, the levels of RCAN1 mRNA were significantly lower in tumor tissues than in normal tissues in bladder cancer." (PMID 35717152, 2022). "Interestingly, the levels of RCAN1 in urine samples of the bladder cancer group were lower than those in the control group." (PMID 35717152, 2022).
cervical squamous cell carcinoma (1 paper, 2022). A squamous cell carcinoma arising from the cervical epithelium. "Increased RCAN1 expression is associated with a lower tumor stage in cervical squamous cell carcinoma and endocervical adenocarcinoma (CESC), head and neck squamous cell carcinoma (HNSC), KIRC, and LIHC and with a higher tumor grade in LGG." (PMID 35717152, 2022).
Cognitive impairment (1 paper, 2022). Abnormal cognition is characterized by deficits in thinking, reasoning, or remembering. "Based on these novel findings, we posit that changes to RCAN1 levels in the brain throughout aging may perturb light-entrained diurnal and circadian activity, which could in turn contribute to aging-related cognitive impairments and/or AD progression." (PMID 35610565, 2022).
degenerative disc diseases (1 paper, 2020). "Nevertheless, evidence regarding the role of RCAN1 in degenerative disc diseases is somewhat limited." (PMID 32467610, 2020).
endometrial adenocarcinoma (1 paper, 2009). "Moreover we have shown that CXCL8 expression in endometrial adenocarcinoma explants is negatively regulated by RCAN1-4 since infection of endometrial adenocarcinoma explants with RCAN1-4 adenovirus abolished the PGF2α-FP receptor-mediated induction of CXCL8." (PMID 19819266, 2009). "Furthermore, infection of endometrial adenocarcinoma explants (P < 0.001) using RCAN1-4 adenovirus significantly reduced the PGF2α-FP receptor induction of CXCL8 mRNA expression compared to tissue infected with the scrambled control virus similar to our in vitro data using Ishikawa FPS cells." (PMID 19819266, 2009).
lung adenocarcinoma (1 paper, 2022). A carcinoma that arises from the lung and is characterized by the presence of malignant glandular epithelial cells. "Upregulated RCAN1 contributes to limiting the growth of lung tumors by suppressing lung adenocarcinoma proliferation and angiogenesis and increasing apoptosis through inhibition of the CN pathway." (PMID 35717152, 2022). "LSL-KrasG12D mice carry a single extra copy of RCAN1 to get inducible and more accurately repeatable molecular features of human lung adenocarcinoma in RCAN1 transgenic mouse." (PMID 35717152, 2022).
myeloid malignancies (1 paper, 2021). "Delineation of the signaling pathways downstream of GPR68 and RCAN1 uncovers novel therapeutic targets that enhance the sensitivity to lenalidomide, especially in R/R and aggressive myeloid malignancies irrespective of del(5q)." (PMID 34680233, 2021).
Neurodevelopmental delay (1 paper, 2025). "Trisomy 21 results in overexpression of key genes (e.g., DYRK1A, RCAN1) involved in neural plasticity and oxidative stress regulation, compounding neurodevelopmental delays." (PMID 41383574, 2025).
non-small cell lung carcinoma (1 paper, 2022). A group of at least three distinct histological types of lung cancer, including non-small cell squamous cell carcinoma, adenocarcinoma, and large cell carcinoma. "The miR-619-5p, an exocrine derived from non-small-cell lung carcinoma (NSCLC), targets RCAN1.4 and promotes angiogenesis of human umbilical vein ECs, proliferation, and metastasis of NSCLC." (PMID 35198064, 2022).
periodontal disease (1 paper, 2016). "Taken together these findings suggest that RCAN1 is involved in the pathogenesis of periodontal diseases." (PMID 27403036, 2016). "The aim of this study was to elucidate the role of RCAN1 in periodontal disease." (PMID 27403036, 2016).
pulmonary hypertension (1 paper, 2025). Increased pressure within the pulmonary circulation due to lung or heart disorder. "In the literature has been described that overexpression of anti-angiogenic genes located on chromosome 21—such as COL4A3, endostatin, and RCAN1—is implicated in impaired vascular development and pulmonary hypoplasia, thereby increasing the risk of pulmonary hypertension in DS patients." (PMID 41462807, 2025).
renal cell carcinoma (1 paper, 2022). "In renal cell carcinoma (RCC), RCAN1.4 restrained tumor progression and metastasis by inhibiting the CN-NFAT signaling pathway." (PMID 35717152, 2022).
renal fibrosis (1 paper, 2021). A final common manifestation of a wide variety of chronic kidney diseases characterized by glomerulosclerosis and tubulointerstitial fibrosis. "Nevertheless, there is still poor understanding of RCAN1 in kidney pathologies including renal fibrosis." (PMID 34707090, 2021). "In summary, we provided evidence that RCAN1.4 played a novel role in the progress of renal fibrosis." (PMID 34707090, 2021). "In addition, knocking in of RCAN1.4 accelerated apoptosis of myofibroblast and attenuated renal fibrosis in vitro." (PMID 34707090, 2021). "However, the role of RCAN1 in renal fibrosis remains unclear." (PMID 34707090, 2021). "Furthermore, the colocalization of RCAN1.4 and α-SMA in both human normal kidney and renal fibrosis tissues were tested by immunofluorescence." (PMID 34707090, 2021).
Respiratory tract infection (1 paper, 2022). An infection of the upper or lower respiratory tract. "Interestingly, the RCAN protein family has vital roles to confer in regulating inflammation; for example, Rcan1 serves a negative regulator of inflammation in response to respiratory tract infections." (PMID 36267816, 2022).
tauopathy (1 paper, 2022). Neurodegenerative disorders involving deposition of abnormal tau protein isoforms (tau proteins) in neurons and glial cells in the brain. "Interestingly, the presence of tauopathy can disrupt biological rhythms, suggesting that RCAN1 overexpression might additively or synergistically perturb the rhythmicity of activity in part through upregulating tau pathology." (PMID 35610565, 2022).
cancer (33 papers, 2010 to 2025). A tumor composed of atypical neoplastic, often pleomorphic cells that invade other tissues. "Conversely, CSRNP1, RND3, and RCAN1 were significantly downregulated, each linked to anti-proliferative or prognostic roles in cancer." (PMID 41216224, 2025). "The RCAN family, particularly RCAN1, has been shown to be associated with the inverse link between AD and cancer as well as related to mitochondrial disruption in AD." (PMID 38002954, 2023). "Here, we have summarized recent studies about the structure, function, and regulation of RCAN1, and their association with various types of cancers." (PMID 35717152, 2022). "Consistently, increased RCAN1 expression inhibits cancer cell migration, while loss of endogenous RCAN1 leads to an increase in migration in a couple of cancer cell lines, such as ARO, WRO, NPA and FTC133." (PMID 29416595, 2018). "In this article, we aim to review the role of RCAN1 in the inverse association and discuss underlying mechanisms, providing an insight into developing a novel approach to treat AD and cancer." (PMID 29416595, 2018). "RCAN1 plays a pivotal role in cell proliferation and migration, which are implicated in both neurogenesis in AD, and tumor growth and metastasis in cancer." (PMID 29416595, 2018). "RCAN1 isoform encodes for protein regulator of calcineurin 1 and its overexpression inhibits migration of cancer cells." (PMID 28330331, 2016). "Therefore, the functions of RCAN1 in cancer pathogenic pathways and its potential as a novel therapeutic target need to be explored." (PMID 35717152, 2022). "RCAN1, associated in the development of DS and AD, is also involved in cancer." (PMID 36012629, 2022). "Accumulated evidence indicates that RCAN1 may play an important role in the inverse association between AD and some types of cancer via both common and differential processes." (PMID 29416595, 2018). "Dysregulation or dysfunction of calcineurin has been linked to both AD and cancer, suggesting that RCAN1 may be involved in the pathogenesis of both AD and cancer via calcineurin-dependent pathways." (PMID 29416595, 2018). "Thus, we aim to review the role of RCAN1 in the inverse association and discuss underlying mechanisms, providing potential strategies for the treatment and prevention of AD and cancer by modulating RCAN1." (PMID 29416595, 2018). "Recent studies indicate that regulator of calcineurin 1 (RCAN1) may play a key role in the inverse association between AD and cancer." (PMID 29416595, 2018). "In addition, RCAN1 expression is associated with human cancer grade and stage." (PMID 35717152, 2022). "It suggests that RCAN1 may play a key role in the inverse association between AD and cancer." (PMID 29416595, 2018). "RCAN1 contributes to deregulation of calcineurin-involved signaling pathways, however, its role to cancer progression is contradictory." (PMID 39835134, 2024). "The cellular component analysis also showed that in both cancers, RCAN1 is significantly enriched in the extracellular matrix, receptor and transporter complexes, and cell–substrate junction." (PMID 37107558, 2023). "To determine expression profiles of RCAN1 in various cancers, we examined data on RCAN1 expression in tumors and normal tissues deposited in The Cancer Genome Atlas (TCGA) database." (PMID 35717152, 2022). "RCAN1 plays a bivalent role in cancer by promoting or attenuating cell apoptosis, inhibiting or promoting cell proliferation and migration, and suppressing or facilitating angiogenesis." (PMID 36012629, 2022). "Above all, RCAN1 has been shown to play diverse roles in regulating cancer development in different organs." (PMID 35717152, 2022). "In other words, the expression of RCAN1 in different cancers can have different roles in tumor progression." (PMID 35717152, 2022). "In contrast, endogenous RCAN1 knockout was found to increase migration in cancer cells in vitro, whereas the expression of exogenous RCAN1 reduced migration." (PMID 36440263, 2022).
cancer (continued). "Together, RCAN1 binds to CN and inhibits CN activity, preventing different cancers via dephosphorylation of antitumor substrates." (PMID 35717152, 2022). "Regulator of calcineurin 1 (RCAN1), as a patent endogenous inhibitor of calcineurin, plays crucial roles in the pathogenesis of cancers." (PMID 35717152, 2022). "Recent studies displayed that RCAN1 hinders the proliferation and angiogenesis of endothelial cells, which regulates the malignant progression of most human cancers." (PMID 33959160, 2021). "Next, to reveal if IFI27 is involved in the mechanism of RCAN1–4’s function in cancer cells, migration and invasion assays were performed in RCAN1.4 knockdown SW1990 cells overexpressing IFI27." (PMID 33824473, 2021). "The roles of RCAN1 in suppressing tumor growth and blocking metastasis have been identified in many types of cancer." (PMID 33824473, 2021). "It came upon that the migratory and invasive abilities of cancer cells were outstandingly reduced with overexpression of RCAN1, whereas the inhibitory effect was notably restored when miR-182-5p and RCAN1 were overexpressed concurrently." (PMID 33959160, 2021). "Then immunohistochemical (IHC) staining of RCAN1.4 was performed in a cohort of breast primary cancer tissues." (PMID 32771023, 2020). "Meanwhile, RCAN1 plays both beneficial role and detrimental role in the pathogenesis of various diseases, such as various CVDs, cancer, and Alzheimer’s disease." (PMID 33267791, 2020). "Increased RCAN1 facilitates cancer cell apoptosis, which is a possible mechanism of inhibiting cancer development and progression." (PMID 29416595, 2018). "Increased expression of regulator of calcineurin 1 (RCAN1) promotes the pathogenesis of AD, while it suppresses cancer growth and progression in many types of cancer." (PMID 29416595, 2018). "Increased and decreased RCAN1 expression are detected in AD and various types of cancer, respectively." (PMID 29416595, 2018). "Increased RCAN1-induced apoptosis promotes AD pathogenesis but suppresses the development and progression of cancer." (PMID 29416595, 2018). "It suggested that dysregulation of RCAN1 plays a key role in the pathogenesis of both AD and cancer." (PMID 29416595, 2018). "Therefore, increased RCAN1 expression may contribute to the reduced incidence of some types of cancer in AD patients, while reduced RCAN1 expression may reduce the risk of AD in patients with various types of cancer." (PMID 29416595, 2018). "The RCAN1 gene was up-regulated in cancer cells, resulting in inhibition of the cell motility, and RCAN1 knockdown was suggested to promote thyroid cancer tumor growth." (PMID 29299148, 2017). "RCAN1 gives rise to abroad cancer suppression via inhibiting the calcineurin pathway in the vascular endothelium in the transgenic mouse model of xenografted tumors." (PMID 28061453, 2017). "Since NF-κB is a popular cancer drug target, the identification of RCAN1 as an NF-κB inhibitor provides a potential treatment for cancer in which NF-κB signaling is aberrantly activated." (PMID 28061453, 2017). "And recent study has verified the RCAN1 can suppress cancer growth by inhibiting NF-κB signaling pathway." (PMID 28061453, 2017). "Consistent with this, studies performed on Rcan1 transgenic mouse have found that Rcan1 gives rise to cancer protection by inhibiting the calcineurin pathway in the vascular endothelium." (PMID 29104573, 2017). "Recent studies show that RCAN1 can attenuate endothelial cell proliferation and angiogenesis, which contributes to malignant progression in most of the major forms of human cancer." (PMID 28061453, 2017). "Since NFAT promotes cancer cell proliferation and invasiveness, RCAN1 serves as a tumor suppressor." (PMID 37107558, 2023). "Moreover, the dysregulation of RCAN1 in various cancers is reviewed, and the potential of targeting RCAN1 as a new therapeutic approach is discussed." (PMID 35717152, 2022).
cancer (continued). "Thus, the present review explores the functions of RCAN1 in cancer pathogenesis and its potential application in the treatment of cancer." (PMID 35717152, 2022). "Therefore, it is crucial to examine the anti-cancer effects of RCAN1 when it is combined with other anti-tumor drugs." (PMID 35717152, 2022). "It is reported that RCAN1 has carcinogenesis and angiogenesis effects in some cancers." (PMID 35717152, 2022). "Recently, accumulating evidence has indicated that RCAN1 is closely involved in the development of cancer and may be a potential therapeutic target." (PMID 35717152, 2022). "Considering its pivotal roles in cancer pathogenesis, targeting RCAN1 and the CN-NFAT pathway may offer a potential therapeutic target for cancer treatment." (PMID 35717152, 2022). "The mechanism of RCAN1 regulation of CN activity in cancer is complex." (PMID 35717152, 2022). "The top intracellular pathways of the 12 overlapping genes were associated with circadian rhythms and entrainment (Arntl, Cry2, Per2, Per3, Bhlhe41), the cell cycle (Cdkn1a, Wee1), the oxytocin signaling pathway (Cdkn1a, Rcan1), and transcriptional misregulation in cancer (Cdkn1a, Per2)." (PMID 33668521, 2021). "Previously, it was documented that RCAN1 acts as a tumor suppressor in various cancers." (PMID 33959160, 2021). "Reduction of endogenous RCAN1 exacerbates cancer cell migration and tumor growth." (PMID 33267791, 2020). "In addition to facilitating Aβ generation and Tau phosphorylation in AD, growing evidence suggests that RCAN1 is involved in several common processes in AD and cancer, such as apoptosis, cell proliferation and angiogenesis." (PMID 29416595, 2018). "Although precisely modulating the expression of RCAN1 may be a potential therapeutic target to treat AD and cancer, several key issues need to be resolved for drug development." (PMID 29416595, 2018). "It suggests that RCAN1 could inhibit cancer development and progression by inhibiting both cancer cell proliferation and migration." (PMID 29416595, 2018). "RCAN1 dysregulation has also been detected in some types of cancer and cancer cells." (PMID 29416595, 2018). "However, increased RCAN1 inhibits cancer development by promoting cancer cell apoptosis, attenuating angiogenesis and inhibiting cancer cell proliferation via calcineurin-dependent or –independent pathways." (PMID 29416595, 2018). "KEGG pathway analysis revealed that in both cancers, RCAN1 may be involved positive regulation of cytokine–cytokine regulation, TGF-β signaling, tumor necrosis factor (TNF) signaling, and cell adhesion, and the negative regulation of pyrimidine metabolism, cell cycle, and DNA replication." (PMID 37107558, 2023). "In addition, RCAN1 targets NFAT which is also activated in several types of cancer." (PMID 36012629, 2022). "Thus, although targeting RCAN1 expression may have therapeutic potential for cancers, there are many challenges that should be considered." (PMID 35717152, 2022). "Thus, RCAN1 expression was reduced in primary HCC compared to adjacent non-cancer liver tissues." (PMID 35717152, 2022). "However, DS is not a proper model to represent the role of RCAN1 in the association between AD and cancer because of the following reasons." (PMID 29416595, 2018). "Moreover, aberrant RCAN1 expression is detected in both AD and various types of cancer." (PMID 29416595, 2018). "In particular, the inhibitory effect of RCAN1 on the CN–NFAT pathway, alone or synergistically with other agents, has been explored in order to shed light on potential treatments for cancer." (PMID 35717152, 2022). "Regulator of calcineurin 1 (RCAN1) is an endogenous protein that is involved in the regulation of the occurrence and progression of a variety of cancers, but currently, people know little about its potential mechanism." (PMID 33959160, 2021).
cancer (continued). "Regulator of calcineurin 1 (RCAN1, also known as Down's syndrome critical region 1 [DSCR1]) is one of the genes located on chromosome 21 which was considered as a tumor suppressor in various cancers." (PMID 37576400, 2023). "All the probes mapping to CpG islands associated with RCAN1 and RCAN3 (vertical bars above CpG islands) presented an unmethylated status in several normal and cancer human cell lines (data not shown), suggesting that these regions may be transcriptionally active." (PMID 24465593, 2014).